COPZ2 (coat protein complex I subunit zeta 2)
Description:
The coatomer is a cytosolic protein complex that binds to dilysine motifs and reversibly associates with Golgi non-clathrin-coated vesicles, which further mediate biosynthetic protein transport from the ER, via the Golgi up to the trans Golgi network. Coatomer complex is required for budding from Golgi membranes, and is essential for the retrograde Golgi-to-ER transport of dilysine-tagged proteins. The zeta subunit may be involved in regulating the coat assembly and, hence, the rate of biosynthetic protein transport due to its association-dissociation properties with the coatomer complex.
Synonyms: MGC23008; zeta2-COP
Tractability: Antibody: UniProt places it where antibodies can reach, with medium confidence. PROTAC: ubiquitination databases record sites on it.
Gene: Protein-coding gene on chromosome 17 (48,026,142 to 48,038,030, reverse strand). Ensembl gene ENSG00000005243.
Subcellular location: Cytoplasm; Endoplasmic reticulum- Golgi intermediate compartment membrane; Golgi apparatus membrane; Cytoplasmic vesicle, COPI-coated vesicle membrane
Pathways (Reactome):
Vesicle-mediated transport: COPI-dependent Golgi-to-ER retrograde traffic; COPI-mediated anterograde transport
Gene Ontology:
Biological process: intra-Golgi vesicle-mediated transport; intracellular protein transport; retrograde vesicle-mediated transport, Golgi to endoplasmic reticulum
Cellular component: COPI vesicle coat; cis-Golgi network; cytosol; endoplasmic reticulum membrane; Golgi membrane; transport vesicle; COPI-coated vesicle membrane; cytoplasm; endoplasmic reticulum-Golgi intermediate compartment membrane
Genetic constraint (gnomAD): Loss-of-function variants: 20 observed, 21.26 expected, observed/expected ratio (o/e) 0.94, 90% interval 0.66 to 1.37. The upper end of that interval is the gene's LOEUF score, 1.37, which puts it in group 5 of 6, group 1 being the genes least tolerant of losing a copy. Missense variants: 174 observed, 169.97 expected, observed/expected ratio (o/e) 1.02, 90% interval 0.9 to 1.16. Synonymous variants: 56 observed, 62.14 expected, observed/expected ratio (o/e) 0.9, 90% interval 0.73 to 1.13.
Homologues: Orthologues: macaque COPZ2 (100% identical), chimpanzee COPZ2 (99% identical), pig COPZ2 (94% identical), rat Copz2 (90% identical), mouse Copz2 (89% identical), guinea pig COPZ2 (86% identical), rabbit COPZ2 (80% identical), dog COPZ2 (78% identical), zebrafish copz2 (65% identical), Drosophila melanogaster zetaCOP (45% identical), Caenorhabditis elegans copz-1 (41% identical), tropical clawed frog copz2 (40% identical). Paralogues in human: COPZ1 (61% identical).
Diseases named in the same sentence as COPZ2 in open-access papers:
COPZ2 is named in the same sentence as 25 diseases in open-access papers, as found by Europe PMC text mining. Sharing a sentence is not in itself a finding about the gene and the disease. The quoted sentences say what the papers report.
glioblastoma (2 papers, 2024). The most malignant astrocytic tumor (WHO grade IV). "The results revealed that COPZ2 expression was significantly upregulated in GBM (glioblastoma IV grade), HNSC (Head and Neck squamous cell carcinoma), KIRC (Kidney renal clear cell carcinoma), LUSC (Lung squamous cell carcinoma)." (PMID 39144445, 2024). "In addition, COPZ2 knockdown significantly inhibited the proliferation, migration, and invasion of glioblastoma cells." (PMID 39144445, 2024).
thyroid cancer (2 papers, 2024 to 2025). "COPZ2 is confirmed to be linked to the prognosis of bladder and thyroid cancer." (PMID 40746884, 2025). "Many studies reported that COPZ2 was differentially expressed in a variety of tumors, such as thyroid cancer, bladder cancer, and hepatocellular carcinoma." (PMID 39144445, 2024).
endometrial cancer (1 paper, 2018). Primary or metastatic malignant neoplasm involving the endometrium (mucous membrane that lines the endometrial cavity). "They found that DNA hypermethylation-mediated silencing of miR-152 and COPZ2 was a relatively frequent molecular event in endometrial cancer and inhibited cell growth in endometrial cancer cell lines, suggesting the epigenetic silencing of these genes to contribute to endometrial carcinogenesis." (PMID 30785618, 2018). "Besides, miR-152 and COPZ2 were both silenced by hypermethylation in endometrial cancer." (PMID 30785618, 2018).
glioma (1 paper, 2024). A benign or malignant brain and spinal cord tumor that arises from glial cells (astrocytes, oligodendrocytes, ependymal cells). "This study highlights the importance of further research into the molecular mechanisms underlying COPZ2’s role in glioma to fully harness its prognostic and therapeutic potential." (PMID 39144445, 2024). "The robustness of these analyses underscores the potential clinical utility of COPZ2 in stratifying glioma patients based on risk and tailoring treatment strategies accordingly." (PMID 39144445, 2024). "To identify the potential mechanism underlying COPZ2-driven malignant behaviors in glioma, we performed a microarray assay using the COPZ2-knockdown and control U251 cell lines." (PMID 39144445, 2024). "The findings of this study reveal a significant association between the expression level of COPZ2 and the disease status of glioma." (PMID 39144445, 2024). "Overall, our study suggests that COPZ2 is a promising diagnostic and prognostic target for glioma patients." (PMID 39144445, 2024). "Given these revelatory insights, COPZ2 could potentially serve as a novel diagnostic or therapeutic target for glioma." (PMID 39144445, 2024). "Notably, Kaplan–Meier survival analysis indicates that elevated COPZ2 expression serves as an independent predictor of overall survival in glioma patients, with higher COPZ2 levels associated with poorer prognosis." (PMID 39144445, 2024). "The high COPZ2 expression was associated with a worse prognosis in glioma (HR = 2.824, p < 0.001)." (PMID 39144445, 2024). "Our results demonstrated that the elevation of COPZ2 was associated with the prognosis and progression of glioma, and it might be a potential diagnostic and prognostic biomarker for glioma." (PMID 39144445, 2024). "Additionally, co-expression analysis and functional enrichment analysis indicate that genes co-expressed with COPZ2 in glioma are predominantly associated with neutrophil-mediated immunity, granulocyte activation, and response to interferon-gamma." (PMID 39144445, 2024). "We found that COPZ2 was highly expressed in glioma and it was associated with age and WHO grades." (PMID 39144445, 2024). "Kaplan–Meier survival curves, Cox analysis, nomogram analysis, and ROC curve showed that COPZ2 was a disadvantageous factor in poor glioma prognosis." (PMID 39144445, 2024). "In univariate Cox regression analysis, the age, WHO grade, 1p/19q codeletion, IDH status, and COPZ2 expression were correlated with OS in glioma patients." (PMID 39144445, 2024). "Future investigations into the mechanisms of COPZ2 in glioma should also consider the interplay and changes between autophagy regulation and vesicle transport." (PMID 39144445, 2024). "Given its central role in vesicular trafficking and its emerging importance in glioma pathology, COPZ2 represents a promising target for therapeutic intervention." (PMID 39144445, 2024). "The outcomes revealed that COPZ2 knockdown impeded the proliferation, migration, and invasion capabilities of glioma cells." (PMID 39144445, 2024). "Aberrant expression of COPZ2 has been detected in glioma tissues compared to normal brain tissues, indicating its potential involvement in tumorigenesis." (PMID 39144445, 2024). "We also conducted in vitro experiments to evaluate the functional role and mechanism of COPZ2 in glioma cell lines." (PMID 39144445, 2024). "Univariable, multivariate Cox regression, Kaplan–Meier methods, nomogram analysis, and ROC curve analysis were carried out to assess the relationship of COPZ2 and other prognostic factors with glioma." (PMID 39144445, 2024). "In essence, the clinical data analysis underscores the potential of COPZ2 as a valuable prognostic biomarker for glioma." (PMID 39144445, 2024). "In this research, we elucidate the crucial role of COPZ2 in glioma through a combination of bioinformatics analysis and experimental investigations." (PMID 39144445, 2024).
glioma (continued). "Clinicopathologic features of low and high COPZ2 expression groups in glioma." (PMID 39144445, 2024). "In addition, we verified that COPZ2 expression levels were upregulated in glioma with TCGA, and Ualcan Databases." (PMID 39144445, 2024). "In glioma, dysregulation of COPZ2 disrupts normal vesicular trafficking and protein sorting." (PMID 39144445, 2024). "In the context of glioma, it has been suggested that COPZ2 may have a significant pathophysiological role." (PMID 39144445, 2024). "Its association with disease severity and patient survival suggests that COPZ2 could be targeted in the development of novel treatment modalities, potentially improving outcomes for glioma patients." (PMID 39144445, 2024). "Notably, the PI3K/AKT pathway, which is often hyperactivated in glioma, can be influenced by COPZ2-mediated vesicular trafficking." (PMID 39144445, 2024). "The LinkedOmics database was used to predict the potential biological mechanism of COPZ2 in glioma." (PMID 39144445, 2024). "In glioma cells, overexpression of COPZ2 might enhance autophagic flux, thereby providing a survival advantage under stress conditions such as hypoxia and nutrient deprivation, common in the tumor microenvironment." (PMID 39144445, 2024). "The IHC also showed that COPZ2 protein expression was higher in glioma tissues." (PMID 39144445, 2024). "Thus, to test whether COPZ2-driven malignant behaviors in glioma cells through PI3K − AKT signaling pathways, rescue experiments were conducted by treating U251 and U87 cells with SC79 (PI3K − AKT signaling pathways activator)." (PMID 39144445, 2024). "Thus, COPZ2 emerges as a pivotal pro-oncogenic factor in the progression of glioma." (PMID 39144445, 2024). "However, COPZ2’s potential involvement in glioma remains to be explored." (PMID 39144445, 2024). "However, no studies focused on the relationship between COPZ2 expression and glioma, and its clinical significance, biological roles, and underlying molecular mechanisms for glioma are still unclear." (PMID 39144445, 2024). "Furthermore, the knockdown of COPZ2 significantly inhibited the proliferation, migration, and invasion abilities of U251 and U87 cells via inhibition of the PI3K/AKT signaling pathway, indicating that COPZ2 could promote the progression of glioma." (PMID 39144445, 2024).
leishmaniasis (1 paper, 2024). Infectious disease that is transmitted through the bite of hematophagous female phlebotomine sand flies. "KEGG pathway analysis revealed that COPZ2 co-expressed genes mainly enriched in leishmaniasis, and staphylococcus aureus infection." (PMID 39144445, 2024).
lung carcinoma (1 paper, 2015). "The other differentially expressed genes have been implicated in various other pathologies such as Peters' plus syndrome with cleft lip/palate (B3GALTL), tumor formation (COPZ2) and lung cancer development (SEZ6L) but have not yet been associated with tooth development." (PMID 25849153, 2015).
thyroid tumor (1 paper, 2015). A benign or malignant neoplasm affecting the thyroid gland. "To assess whether this occurs also in thyroid tumor cells we investigated the expression of COPZ2 by Real Time PCR." (PMID 26431489, 2015). "Interestingly, we also found a significant downregulation of COPZ2 mRNA expression in the majority of thyroid tumor cell lines." (PMID 26431489, 2015). "Whether the thyroid tumor cell dependency upon COPZ1 is related to downregulation of COPZ2 isoform, or to deregulation of other COPI components, as well as the modalities through which COPZ1 inhibition leads to growth suppression of thyroid tumor cells, remains to be investigated." (PMID 26431489, 2015).
tumor (8 papers, 2012 to 2025). "With respect to COPZ1, the susceptibility to its inhibition is related to the tumor-specific downregulation of the paralog gene COPZ2." (PMID 40978486, 2025). "Moreover, they showed that COPZ1 dependency is caused by the tumor-specific downregulation of the paralog gene encoding the COPZ2 isoform, thus introducing the concept of paralog dependency." (PMID 40978486, 2025). "cg21384971 is associated with less expression of the COPZ2 gene, which has been studied as a therapeutic opportunity for proliferation-independent selective killing of tumour cells. cg11220663 is associated with less expression of the ADD2 gene, also known as beta-adducin." (PMID 31142478, 2019). "Two important issues emerged from this study: 1) COPZ1 fits both canonical and paralog dependency definitions; 2) the downregulation of the paralog COPZ2 gene can predict the tumor response to COPZ1 inhibition." (PMID 40978486, 2025). "A previous study showed that overexpression of COPZ2 protected tumor cells from killing by COPZ1 knockdown." (PMID 39144445, 2024). "Mechanistically, COPZ2 suppressed tumor development by participating in the regulation of the PI3K-AKT signaling pathway." (PMID 39144445, 2024). "To explore the discrepancies of COPZ2 expression in human cancers, we compared the differential expression of COPZ2 in various tumor tissues and normal tissues using the TIMER 2.0 database." (PMID 39144445, 2024). "The dysregulation of COPZ2 can disrupt normal vesicular transport and protein processing, leading to altered cell signaling pathways that promote tumor growth and survival." (PMID 39144445, 2024). "Evidence showed down-regulated COPZ2 expression in most tumor cell lines and in individuals with kinds of cancer types." (PMID 31608112, 2019). "Previously we showed the mechanism of selective sensitivity of tumor cells to the inhibition of the ζ-subunit of the COPI complex, encoded by two homologous genes, COPZ1 and COPZ2." (PMID 28223711, 2017). "It has been shown that tumor cells become dependent on COPZ1, as a result of a tumor-specific downregulation of its isoform COPZ2." (PMID 26431489, 2015). "miR-152 and its host gene COPZ2 are silenced in tumor cells and introduction of miR-152 precursor inhibited tumor cell (MDA-MB-231, HeLa) growth." (PMID 22909061, 2012). "In order to corroborate the validity of COPZ1 as tumor target, further efforts should also be dedicated to assess if the effects of COPZ1 inhibition are context-specific or shared by different tumor type models, as well as to validate COPZ2 as a biomarker for patient stratification." (PMID 40978486, 2025). "This raises the possibility that other mechanisms, in addition to COPZ2 downregulation, may be involved in determining tumor cell COPZ1 dependency." (PMID 26431489, 2015). "Specifically, COPZ2 expression correlates positively with WHO grading, indicating higher levels in more advanced grades of the tumor." (PMID 39144445, 2024). "Contrary to the depletion of COPZ1, where COPZ2 expression protects normal cells from Golgi disruption, depletion of ARCN1 disrupted the Golgi equally in normal and tumor cells." (PMID 28223711, 2017). "With respect to control Nthy-ori 3–1 all the tumor cell lines analyzed, but WRO 82–1, showed downregulation of COPZ2 mRNA." (PMID 26431489, 2015).
cancer (6 papers, 2019 to 2025). A tumor composed of atypical neoplastic, often pleomorphic cells that invade other tissues. "Subsequent microarray analysis uncovered differential expression of numerous cancer-related genes and impacted diverse cancer-associated pathways following COPZ2 knockdown." (PMID 39144445, 2024). "High expression of COPZ2 gene is associated with poor prognosis and cancer progression in glioma." (PMID 40978486, 2025). "Furthermore, COPZ2 has been implicated in the regulation of autophagy, a cellular degradation process that is often hijacked by cancer cells to support their metabolic needs and resist apoptosis." (PMID 39144445, 2024). "In addition, high expression of COPZ2 was associated with an unfavorable prognosis in cancer patients." (PMID 39144445, 2024). "The COPZ2 gene is known to be associated with different types of cancer." (PMID 39227733, 2024). "The most difference between them is their expression pattern: COPZ1 expresses in most cancer cells and normal cells, while COPZ2 expresses in the normal cells and is down-regulated in cancer cells." (PMID 37107648, 2023). "Previous research has demonstrated that COPZ1 is indispensable for many types of cancer since the cancer cell possessed a low expression of the isoform COPZ2, including breast cancer, ovarian cancer, and prostate cancer." (PMID 37107648, 2023). "Therefore, it is pointed out that the expression level of the COPZ2 gene could be decreased via silencing microRNA 152 and COPZ1-targeting agents could be deployed to selectively kill different cancer cells." (PMID 39227733, 2024).
COPZ2 also shares sentences with these, for which no sentence is quoted: aortic aneurysm (1 paper); bladder urothelial carcinoma (1); breast carcinoma (1); breast invasive carcinoma (1); cholangiocarcinoma (1); head and neck squamous cell carcinoma (1); kidney chromophobe (1); lip (1); lung adenocarcinoma (1); Lung squamous cell carcinoma (1); Peters plus syndrome (1); prostate adenocarcinoma (1); rectum adenocarcinoma (1); staphylococcus aureus infection (1); stomach adenocarcinoma (1); uterine corpus endometrial carcinoma (1).